GFAP (glial fibrillary acidic protein)
Diseases named in the same sentence as GFAP in open-access papers (continued):
Sharing a sentence is not in itself a finding about the gene and the disease.
Ventriculomegaly (3 papers, 2012 to 2018). An increase in size of the ventricular system of the brain. "Our initial findings suggest that ventriculomegaly in this model is associated with diffuse ependymal GFAP+ reaction, however, any potential causal relationship is currently unknown." (PMID 30319361, 2018). "Using a strategy similar to EPO+MLT to induce multi-faceted repair, intravenous or intraventricular injection of umbilical-cord derived mesenchymal stromal cells on P6 improved early functional outcomes and reduced ventriculomegaly and GFAP-expression in rats with IVH on P4 or P5." (PMID 30319361, 2018). "Notably, in this age-appropriate CAM-IVH model, the degree of GFAP expression appeared to vary inversely with ventriculomegaly." (PMID 30319361, 2018).
vitamin B12 deficiency (3 papers, 2020 to 2022). A disease characterized by low serum levels of vitamin B12, either inherited or acquired. "Western blot results showed that GFAP expression was increased by approx. 60% over control under conditions of vitamin B12 deficiency." (PMID 33050187, 2020).
acute myocardial infarction (2 papers, 2022 to 2025). Necrosis of the myocardium, as a result of interruption of the blood supply to the area. "For fatal TBIs with a survival time of fewer than 2 h, a GFAP CSF concentration of 134 ng/ml discriminates a TBI fatality from control fatalities (acute myocardial infarction, diffuse cerebral hypoxia, and isolated torso trauma) with an accuracy of 78% and a specificity of 94%." (PMID 35226180, 2022). "CSF and serum GFAP levels have been shown to be significantly increased in TBI fatalities compared to myocardial infarction and isolated torso trauma deaths, but not diffuse cerebral hypoxia." (PMID 35226180, 2022). "In serum, GFAP levels peak in acute TBI fatalities (survival times of less than 2 h) and, with increasing TBI survival times up to 456 h, approximate the concentrations of the control group (acute myocardial infarction, diffuse cerebral hypoxia, and isolated torso trauma)." (PMID 35226180, 2022).
acute pancreatitis (2 papers, 2021 to 2022). An acute inflammatory process that leads to necrosis of the pancreatic parenchyma. "Our data also shows a strong tendency for upregulation of GFAP in the hippocampus a week after the induction of acute pancreatitis, despite the resolution of pancreatic inflammatory cells at this timepoint." (PMID 34049483, 2021). "The most common marker of acute pancreatitis is the transformation of quiescent PSCs (positive to glial fibrillary acidic protein (GFAP)) into activated PSCs (positive to α-smooth muscle actin (α-SMA)), and tumor necrosis factor alpha (TNFα) seems to be mainly responsible for its activation." (PMID 35277074, 2022). "We observed that induction of acute pancreatitis increased the tendency for hippocampal CA1 astrocyte reactivity (increased GFAP expression) within 7 days, compared to non-pancreatitis mice, which was not apparent in the XPro1595-treated pancreatitis group." (PMID 34049483, 2021).
acute respiratory failure (2 papers, 2023 to 2024). Life-threatening respiratory failure that develops rapidly. "NF-L and GFAP were increased in critically ill patients undergoing VV-ECMO for acute respiratory failure in whom we had identified CNS injuries on head CT compared with those without." (PMID 38302643, 2024).
Anorexia (2 papers, 2016 to 2025). Lack of desire to eat (loss of appetite). "Consistent with previous research, our study showed a reduction in GFAP-positive astrocytes in the GM (CX) and WM (CC) caused by food deprivation in the ABA model, which was also shown in the dehydration-induced anorexia model." (PMID 40269196, 2025). "We conclude that anorexia reduces the hippocampal GFAP+ cell density and increases vimentin and nestin expression." (PMID 27579183, 2016). "Accordingly, our results showed that GFAP+ cell density and GFAP expression are decreased by anorexia." (PMID 27579183, 2016). "Moreover, reactive astrocytes were increased by anorexia and forced food restriction, indicating that GFAP+ cells react to severe caloric restriction." (PMID 27579183, 2016). "Thus, we conclude that GFAP+ cells and intermediate filament expression are affected by anorexia." (PMID 27579183, 2016). "Accordingly, GFAP+ cells deficit may be replaced by vimentin+/nestin+ cells in anorexia." (PMID 27579183, 2016).
aseptic meningitis (2 papers, 2023). Inflammation of the membranes surrounding the brain and spinal cord without a bacterial pathogen. "glial fibrillary acidic protein astrocytopathy should be a differential diagnosis in patients with aseptic meningitis with movement disorders or autonomic symptoms and elevated cerebrospinal fluid adenosine deaminase." (PMID 37867900, 2023).
brain glioma (2 papers, 2018 to 2023). A malignant glioma that involves the brain. "Glial fibrillary acidic protein (GFAP) in serum is a diagnostic marker of brain glioma presence, with GFAP levels having been demonstrated to provide significant prognostic information." (PMID 30534564, 2018).
central nervous system demyelinating diseases (2 papers, 2024 to 2025). "CSF analysis identified the CNS demyelination disease antibodies with GFAP‐IgG (titer of 1:1 in CSF)." (PMID 38463395, 2024).
central neurocytoma (2 papers, 2022 to 2025). A benign brain tumor composed of neural elements which most often arise from the SEPTUM PELLUCIDUM and the walls of the lateral ventricles. "GFAP immunostaining in central neurocytoma is variable but typically restricted to the background reactive astrocytes." (PMID 35885538, 2022). "GFAP showed minimal to occasional immunostaining of the round neoplastic cells in DNTs and neurocytomas." (PMID 35885538, 2022).
cerebellar degeneration (2 papers, 2016 to 2025). Degeneration of the cerebellum. "Indicators of cerebellar degeneration applied were the Nadler–Evenson method, glial fibrillary acidic protein immunocytochemical, fluoro-jade or anti-calbinidin staining or according to immune reactivity with antibodies against calcium-calmodulin-dependent protein kinase II (Cam KII)." (PMID 27244235, 2016).
Cerebral atrophy (2 papers, 2023). Atrophy (wasting, decrease in size of cells or tissue) affecting the cerebrum. "The first study illustrated increase in global cerebral atrophy scores in relation to serum glial fibrillary acidic protein (GFAP), which were independently associated with CI." (PMID 37288268, 2023).
cerebral malaria (2 papers, 2023 to 2024). A sequestration of Plasmodium falciparum in the brain, which can cause coma and/or seizures. "We aimed to investigate whether a multi-analyte panel including ubiquitin C-terminal hydrolase-L1, neurofilament-light chain, and glial fibrillary acidic protein can serve as biomarkers of brain injury associated with mortality and neurodisability in cerebral malaria and severe malarial anaemia." (PMID 38075948, 2023). "We observed that the corresponding RNA from GFAP and NCAN in plasma EVs from patients with cerebral malaria increased with disease trajectory." (PMID 39151016, 2024). "Median GFAP levels in children with cerebral malaria or severe malarial anaemia were not elevated compared with community children." (PMID 38075948, 2023).
cholestasis (2 papers, 2015 to 2023). Impairment of the bile flow caused by obstruction within the liver, or outside the liver in the bile duct system. "Superresolution imaging of glial fibrillary acidic protein+ astrocytes and RecA+ microvascular endothelial cells confirmed that astrocyte interactions with the BBB were perturbed during cholestasis, but improved with OCA therapy." (PMID 36243043, 2023).
chondropathy (2 papers, 2013 to 2017). "We previously showed that post mortem knee chondropathy scores are significantly and positively correlated with human spinal GFAP mRNA expression 26, confirming the clinical relevance of these spinal markers of central sensitization." (PMID 27860453, 2017). "Spinal GFAP mRNA expression was positively correlated with chondropathy score and with age (Pearsons r value of 0.62 p = 0.04)." (PMID 24282543, 2013). "We also report a positive correlation of spinal GFAP mRNA expression and chondropathy score." (PMID 24282543, 2013). "In addition, associations between spinal expression of GFAP, TRPV1 and COX2 mRNA and macroscopic chondropathy score were also determined in these cases." (PMID 24282543, 2013).
Chronic colitis (2 papers, 2024). A chronic inflammatory disease of the large intestine (colon, cecum and rectum). "However, Wnt ligands from GFAP positive enteric glial cells were important for the high regenerative capacity necessary for the recovery from acute and chronic colitis." (PMID 38322254, 2024).
chronic hepatitis (2 papers, 2006 to 2014). An active inflammatory process affecting the liver for more than six months. "In the frozen chronic hepatitis case (with expected activated hepatic MF and HSC), only nerves in larger portal areas reacted positively to GFAP and NCAM, while synaptophysin did not provoke any signal at all." (PMID 17109742, 2006). "In a frozen chronic hepatitis case (with expected activated hepatic MF and HSC), HSC were negative to synaptophysin, GFAP and NCAM." (PMID 17109742, 2006).
chronic pancreatitis (2 papers, 2011 to 2020). A chronic inflammatory process causing damage and fibrosis of the pancreatic parenchyma. "We found that expression of the fibrosis marker GFAP, α-SMA and the inflammation marker TNF-α, IL-6 increased significantly in chronic pancreatitis when compared to controls." (PMID 32524326, 2020).
co-infection (2 papers, 2018 to 2021). "Brain sections containing hippocampus from saline (SAL), S. pneumoniae (SP), influenza A virus (IAV) or co-infection (SPIAV)-treated mice were immunolabelled for astrocytic marker GFAP and GFAP-positive area were quantified." (PMID 29980196, 2018). "Of importance, four gene products, namely, glial fibrillary acidic protein (GFAP), serpin peptidase inhibitor clade A member 3 (SERPINA3), thymidine phosphorylase (TYMP/ECGF1), and heat shock 70 kDA protein 8 (HSPA8), were confirmed to be abundant in TBM patients with HIV coinfection." (PMID 33087432, 2021).
colon cancer (2 papers, 2022 to 2024). "Spatial tissue mapping via confocal microscopy confirmed proximity between EGCs (GFAP+) and TAMs (F4/80+) within orthotopic colonic tumors injected in C57BL/6J mice, further suggesting the existence of a glial-macrophage interplay within the TME." (PMID 39030280, 2024). "Additionally, Kaplan-Meier survival analysis indicated that colon cancer patients in the GFAP/S100B-HIGH group had a shorter overall survival time than those in the GFAP/S100B-LOW group." (PMID 36522730, 2022).
cortical dysplasia (2 papers, 2021 to 2025). "A prominent component observed in focal cortical dysplasia are the balloon cells, which express glial fibrillary acidic protein (GFAP), an astrocyte intermediate filament." (PMID 34201497, 2021).
cysticercosis (2 papers, 2013 to 2023). "Since neurocysticercosis may trigger an inflammatory response, the expression of Iba-1 and GFAP (two classic markers of inflammation in the brain) was measured on day 120 post-infection." (PMID 37508953, 2023).
cystitis (2 papers, 2020 to 2024). Inflammation of the urinary bladder. "By comparing immunofluorescence staining of the sample tissue, to that in that of the control group, OX-42 and GFAP staining were significantly increased in the SDH of cystitis group; moreover, activated microglia and astrocytes had hypertrophied cell bodies and significantly increased dendrites." (PMID 31931832, 2020). "We conducted an immunofluorescence analysis to measure the expression of endogenous TLR4 ligand HMGB1, and glial activation markers GFAP and IBA1 in lumbar spinal cords, and found that HMGB1, GFAP and IBA1 were downregulated after TAK‐242 injection in the group with cystitis." (PMID 38415918, 2024).
Dyskinesia (2 papers, 2022 to 2024). A movement disorder which consists of effects including diminished voluntary movements and the presence of involuntary movements. "The present study investigated levels of microglia (Iba1 and CD68) and astrocytes (GFAP) markers of inflammation and gliosis in the brain of MPTP monkeys with different levels of dyskinesias induced by L-Dopa and prevented with an added treatment with MPEP a NAM of mGlu5 receptor." (PMID 35203338, 2022).
E. coli infection (2 papers, 2019 to 2025). "It was observed that meningitic E. coli infection of wild-type mice resulted in a notable increase in GFAP fluorescence intensity." (PMID 40929057, 2025).
embryonal carcinoma (2 papers, 2018 to 2024). A non-seminomatous malignant germ cell tumor characterized by the presence of large germ cells with abundant cytoplasm resembling epithelial cells, geographic necrosis, high mitotic activity, and pseudoglandular and pseudopapillary structures formation. "Western blot analysis verified the presence of OCT4, SOX2 and NANOG in hiPSCs and NT2 cells (pluripotent embryonal carcinoma cells, as a positive control), as well as the absence of α-SMA and GFAP." (PMID 30518391, 2018).
encephalomalacia (2 papers, 2022 to 2023). Localized atrophy of the brain parenchyma due to aging, hemorrhage, infarct, or inflammation. "Additionally, astrocyte expansion in regions of encephalomalacia (GFAP+) was observed." (PMID 36435806, 2022). "Similarly, IHC against astrocyte-specific marker glial fibrillary acidic protein (GFAP) showed an increased number of astrocytes or astrocytosis and fibrillary processes per astrocytes or astrogliosis surrounding the region of cryptococcal-induced encephalomalacia and GXM accumulation." (PMID 36656900, 2023).
endometriosis (2 papers, 2021 to 2023). The growth of functional endometrial tissue in anatomic sites outside the uterine body. "On day 16, mice with endometriosis showed significantly more GFAP expression in the hippocampus than shams." (PMID 36879305, 2023). "Regarding studies on glial cells, one study has shown that endometriosis increases GFAP and CD11b expression in the spinal cord of mice with endometriosis." (PMID 36879305, 2023). "Additionally, our findings show increased mast cell degranulation and Iba1 and GFAP expression in endometriosis rat hippocampus." (PMID 34064310, 2021).
endothelial dysfunction (2 papers, 2021 to 2025). In vascular diseases, endothelial dysfunction is a systemic pathological state of the endothelium (the inner lining of blood vessels) and can be broadly defined as an imbalance between vasodilating and vasoconstricting substances produced by (or acting on) the endothelium. "The same findings were reported by other studies in which moderate or deep hypothermia, but also the rewarming phase, were associated with increased GFAP, neuronal cytotoxicity, endothelial dysfunction, inflammation, and loss of vascular brain autoregulation." (PMID 34438546, 2021).
epithelioid sarcoma (2 papers, 2014 to 2024). An aggressive malignant neoplasm of uncertain differentiation, characterized by the presence of epithelioid cells forming nodular patterns. "For proximal-type epithelioid sarcoma, S-100 expression is rare and GFAP is negative." (PMID 25253093, 2014).
fibrosarcoma (2 papers, 2014 to 2015). A malignant mesenchymal fibroblastic neoplasm affecting the soft tissue and bone. "Fibrosarcoma cells express only vimentin and are negative for S-100, GFAP and neurogenic markers." (PMID 24396458, 2014).
focal epilepsy (2 papers, 2021). A seizure caused by a localized disorder. "Another patient with recurrent focal epilepsy who exhibited a 1:32 GFAP antibody titer, lesions in the temporal and occipital lobes on the head MRI, and slow waves in the EEG showed a serum GFAP antibody titer that increased to 1:100 in a retest 6 months later." (PMID 34880859, 2021).
giant axon neuropathy (2 papers, 2019 to 2022). "Gigaxonin is mutated in giant axon neuropathy (OMIM #256850), in which abnormal GFAP aggregation occurs." (PMID 31611638, 2019).
gliomatosis (2 papers, 2013 to 2021). "Histopathological examination showed LM gliomatosis exhibiting rhabdoid tumor cell morphology, necrosis, and extensive loss of GFAP expression." (PMID 33853673, 2021). "The glial features are reflected by positive GFAP and S100 protein in gliomatosis, as well as in the primary tumor." (PMID 23590935, 2013).
head injuries (2 papers, 2020 to 2022). "In 2018, the Food and Drug Administration (FDA) permitted the marketing of a panel of two biomarkers, glial fibrillary acidic protein (GFAP) and ubiquitin C-terminal hydrolase-L1 (UCH-L1), as a screening test for intracranial abnormalities in adults with head injuries presenting to the ED setting." (PMID 36484020, 2022).
Headache (2 papers, 2020 to 2024). Cephalgia, or pain sensed in various parts of the head, not confined to the area of distribution of any nerve. "Recently, antibodies against glial-fibrillary-acidic-protein (GFAP) have described to define an autoimmune astrocytopathy manifesting with meningoencephalomyelitis with headache and subacute encephalopathy." (PMID 33324912, 2020).
HIV dementia (2 papers, 2021 to 2024). "GFAP is present in MDM and astrocytes and is a hallmark of astrocytosis, which is increased in patients with HIV dementia." (PMID 39335448, 2024).
Hyperbilirubinemia (2 papers, 2016 to 2017). An increased amount of bilirubin in the blood. "In particular, in vivo studies of Gunn rat cerebellum indicated that the increase in GFAP content is a common trait of hyperbilirubinemia." (PMID 28340583, 2017). "Hyperbilirubinemia-induced changes in Iba1- and GFAP expression." (PMID 27746740, 2016).
Hypercholesterolemia (2 papers, 2017 to 2024). An increased concentration of cholesterol in the blood. "GFAP-immunohistochemistry was employed to ascertain the effect of hypercholesterolemia on astrogliosis." (PMID 29263397, 2017).
infectious encephalitis (2 papers, 2024). An acute infectious process that affects the brain tissue. "Patients presenting with non-infectious encephalitis and meningeal signs should undergo CSF GFAP antibody tissue- and cell-based testing." (PMID 39449321, 2024). "Currently, the epidemiology of GFAP astrocytopathy remains unclear, but, in a population-based comparative study on the incidence and prevalence of autoimmune and infectious encephalitis in Olmsted County, USA, the prevalence of GFAP astrocytopathy was found to be 0.0006% (0.6/100,000)." (PMID 39464885, 2024).
insomnia (2 papers, 2024). A sleep disorder characterized by difficulty in falling asleep and/or remaining asleep. "In our previous work on an insomnia rat model, several serum biochemical parameters were significantly changed, such as BDNF and GFAP; the concentration of several neurotransmitters in the brain was also different after the application of HWD, including GABA, 5-HT, and glutamate." (PMID 38846089, 2024).
kidney damage (2 papers, 2024 to 2025). "Additionally, due to GFAP’s potential role in maintaining cellular integrity and responding to inflammation, it could serve as an indicator of the progression or severity of kidney damage in inflammatory diseases." (PMID 39459426, 2024).
lentivirus infection (2 papers, 2012 to 2024). Virus diseases caused by the Lentivirus genus. "For instance, lentivirus infection has been demonstrated to produce a dose dependent increase in astrocytic GFAP expression." (PMID 38495109, 2024).
metastatic melanoma (2 papers, 2021 to 2025). A melanoma that has spread from its primary site to another anatomic site. "In an animal model of metastatic melanoma, predominant MAFs expressed glial fibrillary acidic protein (GFAP), which is an HSC marker and negative in local α-SMA-positive fibroblast-like cells, suggesting that MAFs may originate from HSCs." (PMID 34112258, 2021).